LEP (leptin)
Diseases named in the same sentence as LEP in open-access papers (continued):
Sharing a sentence is not in itself a finding about the gene and the disease.
breast cancer (continued). "Additionally, emerging evidence indicates that breast cancer-derived exosomes modulate leptin signalling pathways, further promoting WAT browning." (PMID 41498391, 2026). "Additionally, elevated serum leptin levels in breast cancer patients can directly interact with tumour stroma, activating leptin receptors on cancer cells to induce VEGF production." (PMID 41498391, 2026). "Furthermore, the ratio between leptin/ObR serum levels and the FLI is considered a useful predictor of leptin activity and has been shown to be increased in cases of breast cancer development." (PMID 40902078, 2025). "Additionally, LEP stimulates breast cancer cell proliferation and migration via MAPK pathway activation, and modulates the PI3K/AKT pathway to facilitate epithelial–mesenchymal transition (EMT), migration, and angiogenesis." (PMID 41269404, 2025). "In this regard, leptin may induce B and T cell proliferation and may increase NK cells’ cytotoxicity, supporting the immune response in breast cancer." (PMID 40227577, 2025). "Furthermore, an animal model of breast cancer demonstrated that Fusobacterium nucleatum binds to breast cancer tissues via its leptin Fap2, inhibiting the accumulation of tumor-infiltrating T cells and thereby promoting tumor growth and metastatic progression." (PMID 40575164, 2025). "Leptin’s contribution to tumor cell migration and invasiveness has been documented in various types of cancer, including hepatocellular carcinoma, prostate cancer, and breast cancer." (PMID 40485730, 2025). "Studies in breast cancer survivors have demonstrated that weight-loss interventions preferentially decreased leptin levels (-35.6%) and increased the adiponectin-to-leptin ratio (10.6%), independent of changes in absolute adiponectin levels." (PMID 41555998, 2025). "For instance, Leptin and Insulin levels decreased, particularly in Breast cancer patients, whereas Colorectal cancer patients exhibited a reduction in pro-inflammatory cytokines such as IL-1β, IL-6, IL-8, and TNF-α, even in the absence of weight loss and bioimpedential feature changes." (PMID 41409302, 2025). "A previous study showed that leptin induces VM in breast cancer cells." (PMID 40565190, 2025). "Future research is essential to identify other bioactive components within OB EVs that may act synergistically with leptin, and to validate these mechanisms across diverse breast cancer models, including in vivo systems." (PMID 40485730, 2025). "Moreover, metformin has been shown to reduce body weight, serum cholesterol and leptin in breast cancer patients." (PMID 40374694, 2025). "Furthermore, the addition of leptin and glucose enhances breast cancer cell proliferation and upregulates PPARα, thereby indicating the involvement of PPARα in this process." (PMID 39859448, 2025). "Higher leptin levels, instead, were found in breast cancer (BC)." (PMID 41409302, 2025). "Both leptin and the leptin receptor are overexpressed in primary breast cancer tumors and lymph node metastases, suggesting that this signaling may contribute to cancer progression." (PMID 39609706, 2024). "In addition, genetic variations in the leptin-coding genes LEP and ADIPOQ have been associated with elevated breast cancer risk." (PMID 39251829, 2024). "Leptin had a differential effect on breast cancer cell proliferation." (PMID 38228661, 2024). "Therefore, this study aimed to identify the mechanism by which leptin induces VM, to develop a new treatment that can increase efficiency and survival rate of patients with breast cancer." (PMID 38791252, 2024). "In addition, in postmenopausal breast cancer patients (n=42) there was increased leptin secretion compared to healthy controls." (PMID 39525621, 2024). "Leptin-induced VM was markedly blocked in both breast cancer cells treated with these inhibitors." (PMID 38791252, 2024). "Leptin also increases the activity of the JAG1 receptor NOTCH1 in breast cancer cells." (PMID 39408921, 2024).
breast cancer (continued). "Thus, glucose metabolism requirement for leptin-induced migration varies in different metastatic breast cancer cells." (PMID 39609706, 2024). "Leptin may also play a role in hormone therapy resistance, as leptin levels in the blood increase due to hormone therapy for breast cancer." (PMID 38238841, 2024). "Leptin stimulates the M2 macrophages, thereby promoting breast cancer progression." (PMID 38255203, 2024). "Furthermore, treatment of MDA-MB-231 breast cancer cells with 50 μM of leptin increased migration, and leptin administration increases the primary tumor and the metastasis to the lung of breast tumor cells in vivo." (PMID 39339753, 2024). "COX-2 inhibitors, such as celecoxib, reduce tumor growth in breast cancers, indicating the need for further study to determine whether inhibition of these downstream components affects leptin-induced angiogenesis in a breast cancer context." (PMID 39439572, 2024). "Emerging evidence suggests that elevated leptin levels promote breast cancer progression." (PMID 39339753, 2024). "Accordingly, we hypothesized that autophagy could regulate the energetic metabolic profile of leptin-treated breast cancer cells to sustain tumor processes such as cellular proliferation or migration." (PMID 38228661, 2024). "Leptin-induced IL-8 is pro-angiogenic in several human cancers, including in colorectal and lung cancer, and may also activate angiogenesis in breast cancer." (PMID 39439572, 2024). "Thus, in addition to its other regulatory roles, leptin plays a central role in tumor angiogenesis and metastasis in breast cancer." (PMID 39439572, 2024). "In contrast, leptin, whose expression is increased with obesity, promotes breast cancer growth." (PMID 38888911, 2024). "The impact on cancer cell metabolism remains unclear given that most studies of leptin and breast cancer cell metabolism utilize supraphysiological glucose concentrations." (PMID 39609706, 2024). "AQP1 mRNA was upregulated after leptin treatment for 24 h in both breast cancer cells by RT-PCR." (PMID 38791252, 2024). "Since we show that autophagy is required for ATP production and leptin-enhanced mitochondrial fitness in breast cancer cells, we hypothesized that autophagy and mitochondrial metabolism could be involved in leptin-induced cell migration." (PMID 38228661, 2024). "In our study, 1,25(OH)2D reduced the concentration of leptin present within conditioned media from adipocytes, suggesting that leptin may mediate the impact of 1,25(OH)2D on adipocytes to reduce breast cancer cell migration." (PMID 39339753, 2024). "Interestingly, autophagy inhibition with CQ prevented the increase in maximal respiration and spare respiratory capacity induced by leptin in all breast cancer cells (red bar), indicating the involvement of autophagy in leptin-enhanced mitochondrial function." (PMID 38228661, 2024). "This study demonstrated that leptin triggers VM in both breast cancer cells." (PMID 38791252, 2024). "Furthermore, hyperglycemia plays a role in promoting breast cancer progression by changing leptin/IGFR1 and Akt/mTOR signaling." (PMID 39410536, 2024). "In a model of obese breast cancer in humans, it has been suggested that targeting leptin regulation of cytokine production could be potentially therapeutic by decreasing angiogenesis and regulating stem cell function in breast tumors." (PMID 39439572, 2024). "Dysregulated leptin signaling in breast cancer may influence tumor growth by acting both directly and indirectly on tumor neovascularization and angiogenesis." (PMID 39439572, 2024). "Therefore, this study aimed to investigate the mechanisms by which leptin induces VM in human breast cancer cells." (PMID 38791252, 2024). "Notably, human breast cancer cells exposed to leptin grew more aggressively than unexposed cells, indicating that adipocyte-derived leptin plays a role in driving tumor progression." (PMID 39284708, 2024).
breast cancer (continued). "Therefore, the aim of this study was to evidence the role of autophagy in cancer cell metabolism and to define its relationship with the proliferation and migration of breast cancer cells exposed to leptin." (PMID 38228661, 2024). "In addition, leptin, a product of the Ob gene that is secreted by adipocytes, was found to be overexpressed in nearly 92% of breast carcinomas." (PMID 38247865, 2024). "With overexpression of the leptin gene in breast cancer tissue." (PMID 37686525, 2023). "Within mammary cancer cells and neighboring adipocytes, leptin was shown to be overexpressed." (PMID 37626804, 2023). "Interestingly, leptin and adiponectin, as a pair of antagonists, regulate the proliferation and development of breast cancer cells by binding to leptin receptors." (PMID 37305043, 2023). "We thereby hypothesize that genes coding leptin (LEP) and adiponectin (ADIPOQ) and their receptors are promising candidates in predisposition to breast cancer risk." (PMID 37274250, 2023). "Notably, leptin acts by reducing the number of cells of the G0/G1 phase and incrementing the number of breast cancer cells with the S and G2/M phases, thus supporting cell division and proliferation." (PMID 37509120, 2023). "Likewise, a decrease in leptin, considered a pro-inflammatory adipokine, has been observed in women with breast cancer following a combined training." (PMID 36612320, 2023). "Regarding breast cancer, some studies suggest that leptin could be involved in the development and progression of this pathology." (PMID 37238961, 2023). "Leptin induces breast cancer progression by activating the expression of MMP-2 and MMP-9." (PMID 37686525, 2023). "The Leptin/AMPK signaling pathway may be the key molecular pathway affecting the occurrence of fatigue after chemotherapy in breast cancer patients." (PMID 37542585, 2023). "Our findings supported this hypothesis by showing that LEP gene rs7799039 and ADIPOQ gene rs1501299 were two promising breast cancer-susceptibility loci." (PMID 37274250, 2023). "Overall, LEP gene rs7799039-G allele (odds ratio [OR]: 0.78, 95% confidence interval [CI]: 0.62 to 0.98) and ADIPOQ gene rs1501299-T allele (OR: 1.41, 95% CI: 1.06 to 1.88) were associated with the significant risk of breast cancer." (PMID 37274250, 2023). "The effect of leptin on tumor progression relies on the increased expression of antiapoptotic proteins, such as Bcl-2 and Bcl-xl, which suppress the programmed cell death of breast cancer cells." (PMID 37509120, 2023). "This study is based on RNA-Seq transcriptome sequencing technology to investigate the molecular mechanisms underlying the effect of acupuncture-mediated regulation of the Leptin/AMPK signaling pathway on mitochondrial dysfunction-induced fatigue in breast cancer patients after chemotherapy." (PMID 37542585, 2023). "Particularly, leptin may act by (i) binding its own receptor (ObR) or (ii) by interacting with other different mediators known to be involved in breast cancer biology (e.g., ERα, growth factors, Notch, and inflammatory cytokines)." (PMID 37509120, 2023). "Leptin and IL-1 signaling can activate NF-kB and increase the levels of VEGF and Bcl-2, which could be linked to breast cancer progression." (PMID 37686525, 2023). "Under genotype mode, LEP gene rs7799039-GG was associated with a 22% reduced risk of breast cancer significantly (OR: 0.78, 95% CI: 0.62 to 0.98), and no significance was detected for the other comparisons." (PMID 37274250, 2023). "Additionally, the elevation of leptin signal in the whole body has been related to breast cancer malignancy." (PMID 37620316, 2023). "The association between leptin and EMT has been most well studied in breast cancer." (PMID 37686525, 2023). "Several studies reported that leptin and leptin receptors might be involved in the development and progression of tumors, including colorectal cancer, breast cancer, and hepatic cancer." (PMID 37509115, 2023).
breast cancer (continued). "Indirectly, higher levels of estrogen may upregulate leptin production, which may also be relevant for breast cancer development." (PMID 36831637, 2023). "Through transcriptome sequencing, we found that the Leptin/AMPK signaling pathway may be a key molecular pathway affecting the occurrence of fatigue in breast cancer patients after chemotherapy." (PMID 37542585, 2023). "Under dominant mode, the protective effects of LEP gene rs7799039 GG plus GA genotypes and LEPR gene rs1137100 AA plus AG genotypes on breast cancer risk dwindled, and the risk conferred by ADIPOQ gene rs1501299 TT plus TG genotypes was enhanced, with OR of 1.41 (95% CI: 1.06 to 1.88)." (PMID 37274250, 2023). "Thus, in many cancers such as breast cancer, cytokines including leptin, IL-1B, IL-6, IL-8, IL-23, IL-17, and IL-10 stimulate while others including IL-2, IL-12, and IFN-γ, inhibit cancer proliferation and/or invasion and enhance the body’s anti-tumor defense." (PMID 36835413, 2023). "In addition to IGF-1, estrogen is critical in breast cancer, and adiponectin is receiving increasing attention in pancreatic cancer; leptin and adiponectin have been relatively less studied in endocrine-related cancers." (PMID 36755926, 2023). "Leptin promotes cell proliferation and the development of breast cancers and may be a potential biomarker of breast cancer risk in women, especially overweight/obese or postmenopausal women." (PMID 36835413, 2023). "Leptin may improve post-chemotherapy fatigue in breast cancer patients by activating AMPK phosphorylation and alleviating mitochondrial functional impairment." (PMID 37542585, 2023). "Previous large cohort studies also reported elevated serum leptin levels in breast cancer patients." (PMID 37620316, 2023). "In addition, it has been shown how leptin signaling may potentiate ERα’s role in a lysine to arginine mutation at residue 303 (K303R) within the hinge domain of ERα, which promotes the growth and progression of breast cancer, especially in K303R-associated breast cancer." (PMID 37509120, 2023). "Moreover, the LDFI antagonist hampers leptin’s role in cell-cell paracrine interactions by reducing exosome release from breast cancer cells." (PMID 37509120, 2023). "In addition, leptin can also promote the proliferation of breast cancer cells in vitro through steroid receptor coactivator (SRC) -1/STAT3 signal pathway." (PMID 37305043, 2023). "Leptin drives breast cancer cell proliferation while increasing GLUT-1 mRNA levels." (PMID 37233716, 2023). "Therefore, the critical role of leptin in pathogenesis provides potential therapeutic strategies for breast cancer." (PMID 36794014, 2023). "While many recent meta-analyses revealed a strong association of high levels of certain adipokines (adiponectin, leptin) with breast cancer, inter-population variability may limit its generalizability as a biomarker for disease prognosis and progression." (PMID 36900364, 2023). "Importantly, we found that LEP gene rs7799039 and ADIPOQ gene rs1501299 were two promising candidate loci in predisposition to breast cancer risk." (PMID 37274250, 2023). "Leptin has greater effects on ER+ breast cancer proliferation and EMT than in ER− breast cancer." (PMID 37233716, 2023). "Wnt signalling within adipocytes promotes stemness, as demonstrated in breast cancer where adipocyte-secreted IL-6 and leptin activate breast cancer stem cells through Notch, Wnt, and Sex determining region Y-box 2/octamer binding transcription factor 4/Nanog signalling." (PMID 38136392, 2023). "Moreover, we discussed leptin and MMPs as emerging biomarker targets with potential use for managing pancreatic cancer based on breast cancer studies in the future, based on inflammatory mechanisms." (PMID 37181043, 2023).
breast cancer (continued). "In addition to adipocyte-produced leptin, endogenous leptin expressed in tumors also stimulates the growth and invasiveness of malignant cells, as shown in studies of breast cancer, non-small cell lung cancer, and melanoma." (PMID 37895840, 2023). "Notably, leptin has been shown to increase protein levels of TGFβ1 in ER + and ER- breast cancer cells (MCF7, MCF10AT1) and a neutralising antibody against TGFβ1 blocks leptin-mediated actions." (PMID 36038791, 2022). "The association of LEP/LEPR genetic variations with risk of ER+/PR+ and ER-/PR- breast cancer." (PMID 35223490, 2022). "Besides, adipocytes promoted breast cancer progression by secreting metabolic substrates, such as leptin, which stimulated hypoxia at tumor sites." (PMID 35155430, 2022). "Overall, our results indicate that leptin by inducing the release of EV-enriched in mitochondrial proteins may control the metabolism of MCF-7 breast cancer cells as well as that of macrophages." (PMID 36361728, 2022). "In line with this evidence, our current findings revealed that in breast cancer cells, the adipokine leptin might influence tumor metabolism, by inducing the release of EVs enriched in molecular component of mitochondrial energetic machinery." (PMID 36361728, 2022). "Furthermore, LEP in mouse mammary cancer cells models (4T1, EMT6, and MMT) appeared to promote angiogenesis through VEGF up-regulation via canonic (JAK/STAT, MAPK, PI3K) and non-canonical (PKC, JN) signaling cascade." (PMID 36291602, 2022). "Elevated leptin levels after treatment and consequently increased recurrence and mortality rates in breast cancer patients may be due to resistance to chemotherapy." (PMID 36556428, 2022). "Studies have shown that the secretion of various factors, including leptin, insulin‐like growth factor 1, and oncostatin M, from hASCs could promote breast cancer." (PMID 35600659, 2022). "In addition, leptin promoted breast cancer cell migration and invasion via FAK-Src-dependent manner in vitro." (PMID 35701840, 2022). "Leptin upregulates telomerase activity as well as the mRNA and protein levels of the catalytic subunit of reverse transcriptase of human telomerase (hTERT) in breast cancer cells (MCF-7)." (PMID 36038791, 2022). "Elevated leptin mRNA levels were detected in tissue samples of patients with breast cancer." (PMID 35778755, 2022). "Leptin impacts breast cancer biology through a myriad of mechanisms that result in increased tumor volume and metastasis in preclinical and clinical models of breast cancer, including TNBC." (PMID 35752704, 2022). "Leptin mediates the bidirectional action between breast cancer cells and TAMs." (PMID 35701840, 2022). "Leptin and leptin/adiponectin ratio showed negative associations with breast cancer risk in univariate models, that were attenuated when adiposity was accounted for." (PMID 35948877, 2022). "In addition, studies also showed that variants of LEP and LEPR gene are associated with breast cancer susceptibility." (PMID 35223490, 2022). "According to them, leptin may have an autocrine promoting effect on breast cancer carcinogenesis and its inhibition may be effective in the treatment of breast cancer." (PMID 36556428, 2022). "Clinical data have also confirmed the correlation between high serum leptin and breast cancer." (PMID 36077676, 2022). "Indeed, in a study conducted on 87 breast cancer patients treated with neoadjuvant chemotherapy, LEP and LEPR overexpression, were found in patients with higher levels of tumor-infiltrating lymphocytes (TILs)." (PMID 36291602, 2022). "During the breast cancer progression, TSAs stimulated by external conditions can oversecrete leptin, which could bind to receptors on tumor cells and exert biological effects, triggering the effects on proliferation, migration, and tumor invasion." (PMID 35701840, 2022).